RAC1 (Rac family small GTPase 1)
Diseases named in the same sentence as RAC1 in open-access papers (continued):
Sharing a sentence is not in itself a finding about the gene and the disease.
melanoma (continued). "From Liang’s cohort in the cBioPortal database, we found that high expression of RAC1 suggested worse OS and disease-free survival (DFS) in acral melanoma patients." (PMID 35534866, 2022). "In melanoma, the transcription factor complex SRF/MRTF is a key RAC1 effector, which has generated a therapeutic resistance by inducing a mesenchymal-like state." (PMID 34804979, 2021). "RAC1 through PAK1, Merlin and the cytoskeleton renders the melanoma cells a higher metastatic potential and higher proliferation rate of metastatic cells." (PMID 34827551, 2021). "Alterations in other important constituents of the PI3K/AKT pathway, namely RAC1, PIK3CA, AKT3, PREX2, and AKT1, are also known to occur in melanoma." (PMID 35008286, 2021). "Current investigations demonstrate that Rac1 induces nuclear alterations through microtubules and LINC complex to promote an invasive phenotype in melanoma cells." (PMID 34440759, 2021). "However, clinical inhibitors of RAC1 are not currently available although SRF/MRTF inhibitors in combination with BRAF inhibitors have been recently demonstrated to have utility in the treatment of BRAF mutant melanoma with an RAC1 P29S mutation." (PMID 32850962, 2020). "In melanoma, it was previously shown that DOCK3, a Rac1-specific guanine nucleotide exchange factor (GEF), is required for mesenchymal movement, whereas the Rac1 suppressor ARHGAP22 has an inhibitory effect." (PMID 33202906, 2020). "Clinically, CDC42, RAC1, and RHOA expression in patient samples can provide relevant knowledge about melanoma thickness, ulceration, prognosis, and drug resistance." (PMID 33072757, 2020). "Particularly, Arf6 role on melanoma progression and tumorigenesis is mediated by Ras/RAF/MEK/ERK signaling pathway, which activates Rac1, leading to cytoskeleton remodeling and the formation of invadopodia." (PMID 33072757, 2020). "Specifically, CAV1 was shown to activate a novel CAV1/Rab5/Rac-1 signaling axis that requires phosphorylation of CAV1 on tyrosine-14, which is also essential in B16F10 melanomas to promote lung metastasis." (PMID 31484460, 2019). "Changes affecting many other genes are also common, particularly in advanced melanoma, including ARID2, RAC1, and SF3B1, amongst many others." (PMID 31861163, 2019). "However, small molecule inhibitors against RAC1 have not been tested in clinical trials up to now, which might be due to the relatively small percentage of melanoma patients affected by this mutation." (PMID 30987166, 2019). "Five SNPs, namely rs1049255 (CYBA), rs4673 (CYBA), rs10951982 (RAC1), rs8031 (SOD2), and rs2536512 (SOD3), exhibited significant genotypic frequency differences between melanoma cases and healthy controls." (PMID 29342889, 2018). "A truncating mutant of PREX2 in melanoma has increased Rac1 GEF activity, and activates PI3K/AKT signaling, while abolishing binding to the PTEN tumor suppressor in melanoma." (PMID 30261690, 2018). "In melanoma cells, CAV1 expression induces an increase in cell migration and invasion by the activation of Rac1." (PMID 29340103, 2017). "Mechanistically, we show that SPRY4 is negatively regulated by MT1-MMP via an MMP2/RAC1 pathway, and importantly, negatively modulates MT1-MMP dependent cell migration in melanoma cells." (PMID 26392417, 2015). "The cordycepin treatment downregulated the expression of ZEB1, HMGA2 and TWIST1 by more than 50% but had minimal effects on ADAM9, RAC1, SALL4, CTNNB1, ZEB2 and YES1 in these two melanoma cell lines." (PMID 25868853, 2015). "Rac1 activation through ROCK inhibition in MCF-7 cells was expected, as ROCK antagonizes RhoA-dependent Rac1 activation in fibroblasts, and Rac inactivation through ROCK is occurs via FilGAP phosphorylation or ARHGAP22 activation in melanoma cells." (PMID 24523903, 2014).
melanoma (continued). "Knockdown of Vav1 by RNAi in melanoma cells led to impaired activation of the Jak/Vav1/RhoGTPases (Rac1 and RhoA) pathway, blocking up-regulation of MT1-MMP by CXCL12, a mechanism that contributes to melanoma cell invasion." (PMID 25313137, 2014). "Indeed, in response to a protease inhibitors-rich milieu, prostate and melanoma cells activated an amoeboid invasion program connoted by retraction of cell protrusions, RhoA-mediated rounding of the cell body, formation of a cortical ring of actin and a reduction of Rac-1 activation." (PMID 24681666, 2014). "More recently, deep-sequencing approaches of melanoma samples of different melanoma types highlighted new melanoma driver genes such as PREX2, PPP6C, and RAC1." (PMID 24416617, 2013). "For example, in melanoma, overexpression of SH3BP1 promotes the expression of Rac1 and Wave2, which promotes melanoma proliferation, invasion, and migration through the SH3BP1/Rac1/Wave2 pathway." (PMID 40688112, 2025). "Given our observation that RAC1-amplified HNSCC were pharmacologically vulnerable to EHop-016, we tested the hypothesis that RAC1-amp status in other cancer, such as melanoma, might also confer sensitivity to Rac1 targeting using EHop-016." (PMID 39941730, 2025). "Despite the pleiotropy of the Rac1-driven resistance pathways, we identified focal adhesion kinase (FAK) inhibition as a promising strategy for the treatment of Rac1-driven drug-resistance in melanoma." (PMID 41109929, 2025). "Given the resilience of multiple Rac1-driven cells to BRAFi/MEKi treatment, we wondered whether these cells might be truly ERK-independent, as previously suggested for certain classes of Rac1/PAK-driven, BRAFi/MEKi-resistant melanoma cells." (PMID 41109929, 2025). "Among genes involved in driving melanoma progression, Rhoa expression was reduced by a factor of three after treatment with both cfDNAs, whereas Rac1 expression did not change." (PMID 38791341, 2024). "Patient #27, indeed, had multiple recognized melanoma drivers including BRAF p.V600K, RAC1 p.P29S, pTERT C228T and KRAS p.G12A, this latter arising at the time of progression; thus, patient #27 represents a good example of a combined intrinsic (RAC1 mutation) and acquired (KRAS mutation) resistance." (PMID 38548846, 2024). "Similarly, dieckol inhibits ROS-mediated Rac1 activation and WAVE2 expression, resulting in reduced B16 melanoma cell motility and invasion." (PMID 35736190, 2022). "However, the growth of the intrinsically drug-resistant melanomas (A2058, RPMI7951, vRPP1, and vRPP3) was reduced by RAC1-knockdown either in standard conditions (RPMI7951, vRPP1, vRPP3) and/or during BRAFi (A2058, vRPP3)." (PMID 36271142, 2022). "To conclude, the increase of PCDH9 could suppress melanoma cells by observing the deregulation of MMP2, MMP9, and RAC1." (PMID 36452505, 2022). "PCDH9 and CCND1 (Cyclin D1) exhibited a positive correlation, whereas MMP2, MMP9, and RAC1 exhibited a negative correlation with both melanoma A375 and G361 cells." (PMID 36452505, 2022). "We were curious why some of the melanoma cell lines we studied were not sensitized to BRAFi upon RAC1-knockdown." (PMID 36271142, 2022). "RAC1/P29S expression alone in mouse melanocytes did not result in melanoma; however, in combination with mutant BRAF, RAC1/P29S expression resulted in melanoma in these mice." (PMID 35454871, 2022). "Knockdown of WNT5A expression not only decreased melanoma cell invasion but also resulted in a significant reduction in Cdc42 activity but no change in Rac1 activity in either cell line." (PMID 33969605, 2021). "On the other hand CYT-low metastatic melanomas had recurrent amplifications in loci 5p15.33 (TERT), 6p25.1 (CDYL), 7p22.2 (RAC1), 12q15 (MDM1) and recurrent deletions in 5q31.2 (CTNNA1, FGF1), 11q22.3 (FDX1, RDX, ZC3H12C), and 15q14 (RASGRP1, CSNK1A1P1, SPRED1)." (PMID 33779796, 2021).
melanoma (continued). "Contrary to some primary melanoma, that can harbor both BRAF and RAC1 mutations simultaneously, these mutations are not concomitantly found in papillary thyroid cancer according to TCGA (analyzed using cBioPortal)." (PMID 34638434, 2021). "We then explored whether the reduced activity of Cdc42 is responsible for the impaired invasion of melanoma cells upon reduced WNT5A expression through gain‐of‐function experiments with the Cdc42 and Rac1 activator II." (PMID 33969605, 2021). "RAC1 is found to be mutually exclusive with MYH9, a tumor suppressor in melanoma." (PMID 34899838, 2021). "Moreover, using melanoma patient samples in TCGA, they identified a positive correlation between PD-L1 expression and RAC1P29S status when compared to wildtype and other RAC1 mutants." (PMID 34827551, 2021). "RAC1 was previously pointed out as a key downstream effector of NRAS Q61K for tumor growth in melanoma, but no study has been conducted in thyroid cancer." (PMID 34831012, 2021). "In addition to CDC42 and RAC1 GTPases, RHOA is also part of molecular networks crucial for the control of melanoma proliferation, migration, and invasion." (PMID 33072757, 2020). "We found that VGSC activator vetratridine at concentrations that abolished amide-linked local anesthesia-induced membrane depolarization did not affect melanoma cell RhoA, Rac1 or Ras activity." (PMID 32085741, 2020). "In contrast, bupivacaine which did not display inhibitory effects on melanoma cells did not affect RhoA, Rac1 and Ras activities, suggesting the specific inhibitory effects of ropivacaine on these small GTPases." (PMID 32085741, 2020). "RAC1 codon 61 mutations are not found in human melanoma, but RAC1Q61L served as a control for increased RAC1 signaling." (PMID 31257073, 2019). "RAC1 function is also known to be essential in KRAS induced tumor formation, and in KRAS oncogene addiction, so the potential exists for SRF/MRTF inhibition to be explored in a far greater range of tumors than just RAC1P29S melanoma." (PMID 31257073, 2019). "In the TCGA melanoma cohort, with or without BRAFmut, RAC1P29S/L mutation, or RAC1 overexpression is also associated with relapse." (PMID 31257073, 2019). "Even though rs10951982 in RAC1 has not yet been reported in ROS-related malignancies, somatic mutations of RAC1 (e.g., RAC1P29S) were found in 9.2% of sun-exposed melanoma tumors." (PMID 29342889, 2018). "In addition, RAC1 is also a crucial kinase in the NRAS and PI3K pathway, both of which are key melanoma oncogenic pathways." (PMID 29342889, 2018). "However, the characterization in vitro of both B16F10 and A375 melanomas shows that CAV1 expression enhances migration and Rac1 activation 4,19 as well as invasion in a matrigel assay (data not shown)." (PMID 24500501, 2014). "Unlike the overexpression of Rac1, RhoA activity in B16 melanoma cells exhibited no significant change in the short period after narrow-band UVB irradiation, although a delayed elevation was observed." (PMID 24649261, 2013). "Therefore, we first created subclones of A375 melanoma cells with stable shRNA-mediated Rac1 knockdown (Rac1 KD) or cells harboring a non-targeting shRNA (NT)." (PMID 41109929, 2025). "Monomeric GTPases such as Rac1 are activated by guanine exchange factors (GEFs), and we previously identified upregulated DBL family member GEFs, including Vav1, as drivers of resistance to BRAF inhibitors (BRAFi) in a forward genetic screen using BRAF-mutant melanoma cells." (PMID 41109929, 2025). "Importantly, although Rac1-driven melanoma cells display reduced dependence on BRAF/MEK, they are not completely ERK-independent." (PMID 41109929, 2025). "Targeting the RAC1-GTPase pathway, including the upstream activator PREX2 and the downstream effector PI3Kβ, could be a potential strategy for overcoming therapeutic resistance, limiting melanoma recurrence, and suppressing metastatic progression." (PMID 39636745, 2025).
melanoma (continued). "One study found that in melanoma cells, lidocaine and ropivacaine, but not bupivacaine, decreased Ras, RhoA, and Rac1 expression, and augmented the antimigratory, antiproliferative and pro-apoptotic effects of the chemotherapeutic agents vemurafenib and dacarbazine when used in combination." (PMID 38741694, 2024). "Noteworthy was also the observation from the 3-institution cohort that genetic aberrations of specific melanoma-associated genes were less frequent in APC/CTNNB1-mutant stage IV melanomas than the incidence of these mutations without (e.g., NF1, RAC1, and PTEN)." (PMID 34986841, 2022). "However, RAC1P29S unexpectedly slowed the growth of three melanomas that were not impacted by RAC1-depletion." (PMID 36271142, 2022). "In contrast to RAC1, no mutations in RHOA have been detected thus far in melanoma; still, low expression of RHOA was reported to be associated with a poorer prognostic in a cohort of melanoma patients." (PMID 34503171, 2021). "Additionally, ropivacaine decreased RhoA and Ras activities to a larger extent than Rac1 activity, suggesting that the dominant effects of ropivacaine are inhibition of RhoA and Ras rather than Rac1 in melanoma cells." (PMID 32085741, 2020). "However, in BRAFi‐R melanoma cells, no data are available regarding possible altered Cdc42/Rac1‐GTPase activities." (PMID 30582770, 2019). "RAC1 also affects 3D cell motility and inhibits RHO-ROCK signaling, further highlighting that the presence and high frequency of RAC1P29S in melanoma cases may have implications on both melanoma metastasis and survival in these patients." (PMID 30460237, 2018). "We compared rounded-contractile A375M2 melanoma cells with more elongated ROCK-inhibited A375M2 cells (treated with H1152, Y27632, or Fasudil for 24 hours) (P = .0047, P < .001, P < .001) or with intrinsically less contractile A375P cells, with higher Rac1 activity." (PMID 26464464, 2016). "Furthermore, melanoma cells with high levels of RHO-ROCK-actomyosin have developed mechanisms to allow fast migration in physiological 3-dimensional (3D) environments and inhibit excessive RAC1-mediated cell adhesion." (PMID 27308633, 2016). "Therefore, despite the pleiotropic mechanisms of Rac1-driven MAPKi resistance, we find that combined inhibition of RAF and MEK with the RAF/MEK clamp avutometinib and FAK with the FAK inhibitor defactinib is a promising approach for suppressing the growth of Rac1-driven melanoma cells." (PMID 41109929, 2025). "Perhaps a negative feedback loop exists between RAC1 and MITF, as the growth of differentiated melanomas critically depends on MITF and that deletion of MITF results in the rampant activation of Rho family GTPases40." (PMID 36271142, 2022). "The noncanonical EPHA2 promoted a switch from RAC1 to CDC42 (and RHOA) to increase the invasion and PI3K-dependent p-MLC2 levels in therapy-naïve melanomas." (PMID 35159327, 2022). "Which downstream effectors of RAC1 might be important in melanoma is not known, although a recent report has highlighted a potential role for PAK in a zebrafish model and in human melanoma cell lines." (PMID 31257073, 2019). "Moreover, we extracted the transcriptome data of 34 patients with acral melanoma from Liang’s cohort through the cBioPortal database and found a negative correlation between FMRP mRNA and RAC1 mRNA, further confirming that FMRP is involved in regulation of RAC1 nontranslational pathways in melanoma." (PMID 35534866, 2022). "Overall, 30% of melanomas show alterations in either PREX1 or PREX2, although the functional significance of most of these individual changes has not been tested and may not all be mediated through RAC1 signaling." (PMID 31257073, 2019). "However, we did not observe a significant reduction in Rac1‐GTPase activity in HTB63‐R cells treated with the combination of IL‐6 Ab and Box5, arguing against an essential role of Rac1 in the IL‐6‐ and WNT5A‐dependent invasive migration of BRAFi‐R melanoma cells." (PMID 30582770, 2019).
lung cancer (115 papers, 2010 to 2026). A malignant neoplasm involving the lung. "RAC1 activating mutations alone are insufficient to initiate carcinogenesis in skin, colorectal and lung cancer, but cooperation with BRAF or KRAS mutations results in enhanced proliferation and accelerated tumour growth." (PMID 40396280, 2024). "Our research team has confirmed that Rac1 can target the PAK1-LIMK1-Cofilins signaling pathway to cause radiotherapy resistance in lung cancer." (PMID 34079763, 2021). "We have found that RAC1 polymorphisms are associated with platinum-based chemotherapy toxicity in lung cancer patients in our previous study." (PMID 32848724, 2020). "For example, it was recently shown that TRAIL/TRAILR2 signaling increases migration and invasion via a Rac1/PI3K signaling axis in KRAS mutated nonsmall-cell lung cancer and pancreatic ductal adenocarcinomas." (PMID 32433558, 2020). "Our study investigated the association between HSPs, RAC1 and RhoA and the survival time in Chinese lung cancer patients treated with platinum-based chemotherapy." (PMID 32848724, 2020). "Our data has demonstrated that genetic targeting of RAC1 by siRNA causes a significant reduction in cell proliferation and metastasis of lung cancer cells." (PMID 31779616, 2019). "It has been reported that RAC1 or RhoA are mutated in cancers, and the expression levels of RAC1 or RhoA are aslo altered, which means that RhoA may play an crucial role in lung cancer treatment." (PMID 32848724, 2020). "Higher RAC1 expression were significantly associated with poor prognosis in lung cancer patients." (PMID 31779616, 2019). "Moreover, higher levels of RAC1 was significantly associated with poor prognosis of lung cancer patients." (PMID 31779616, 2019). "RAC1 knockdown reduces cell proliferation and metastasis in breast and lung cancer cells, suggesting its oncogenic potential." (PMID 39898257, 2025). "In lung cancer, Rho GTPases, especially RhoA, Rac1, and Cdc42, play key roles in tumor progression and metastasis." (PMID 39870629, 2025). "Together, the findings delineate functional differences and underlying mechanisms of RAC1 isoforms in LUAD tumorigenesis, highlighting a promising therapeutic route via targeting RAC1B for lung cancer." (PMID 40548642, 2025). "In lung cancer, a study has indicated that RAC1 is highly expressed in circulating tumor cells and lung metastatic cells." (PMID 39898257, 2025). "By combining the PB1 domain of PKCι, blocking its interaction with Par6, inhibiting the downstream Rac1–Pak–Mek1/2–Erk1/2 signaling pathway, thereby inhibiting lung cancer cell proliferation." (PMID 41244006, 2025). "Recently, Rac-GEFs responsible for Rac1-mediated lung cancer cell migration upon EGFR and c-Met activation have been identified." (PMID 38612674, 2024). "Prior reports suggesting HACE1-mediated RAC1 ubiquitination repressed the proliferation of breast and lung cancer cells further corroborate the notion that HACE1 suppresses ESCA progression through RAC1 ubiquitination 39-40." (PMID 38706891, 2024). "Inhibition of RAC1 attenuates the proliferation, invasiveness and migration ability of lung cancer cells." (PMID 37202394, 2023). "In lung cancer tissues, RAC1 expression was dramatically increased, and knockdown of RAC1 remarkably decreased cell migration, invasion, and proliferation." (PMID 37620594, 2023). "Functional activities of Rac1 correlating with the enhanced activation of Akt and GSK3β play an important role in lung cancer metastasis." (PMID 37612265, 2023). "Two of five RAC1-OE mice showed high signal shadows in the brain parenchyma, indicating that the lung cancer cells metastasized to the brain using the MRI T2WI sequences." (PMID 37202394, 2023). "In the present study we obtained a more comprehensive picture over lung cancer metastasis in the single-cell level, giving a new perspective to the role of RAC1 in the LUAD brain metastasis, and related pathways to participate in the metastasis process." (PMID 37202394, 2023).